HACE1 (HECT domain and ankyrin repeat containing E3 ubiquitin protein ligase 1)
Diseases named in the same sentence as HACE1 in open-access papers (continued):
Sharing a sentence is not in itself a finding about the gene and the disease.
cancer (28 papers, 2012 to 2025). A tumor composed of atypical neoplastic, often pleomorphic cells that invade other tissues. "The deficiency of HACE1 leads to the hyperactivation of Rac1, resulting in increased cellular malignancy and invasiveness, thereby promoting cancer progression." (PMID 40948788, 2025). "HACE1 has been primarily implicated in tumorigenesis and cancer progression as a tumor suppressor gene, according to its inactivation in Wilms’ tumors and other cancers as well as its reduced expression in colon and gastric cancers." (PMID 34943902, 2021). "Our study of the functional interplay between HACE1 and Rac1 in cancer thus sheds a new light on the molecular mechanism of Rac1 ubiquitylation by HACE1 and the impact of its cancer-associated mutations in cell proliferation." (PMID 28317937, 2017). "Our analysis of cancer-associated mutations in HACE1 pointed to a critical role of the ANK domain in coordinating the association of HACE1 with Rac1 for its ubiquitylation by the HECT domain." (PMID 28317937, 2017). "We concluded from this analysis that missense mutations found in cancer samples outside the catalytic domain of HACE1 alleviate its capacity to bridle cell proliferation." (PMID 28317937, 2017). "We identify for the first time cancer-associated missense mutations that alter HACE1 regulatory function in cell proliferation." (PMID 28317937, 2017). "HACE1 deficient mice are spontaneously prone to developing multiple malignant tumors in various organs." (PMID 34707697, 2012). "Interestingly, the restriction of proliferation conferred by expression of wild-type HACE1 was diminished by all the cancer-associated mutations identified in our study." (PMID 28317937, 2017). "HACE1-deficient mice developed spontaneous, late-onset cancer." (PMID 27213432, 2016). "To determine whether HACE1 loss also occurs in other cancer types, we queried HACE1 expression and/or copy number in multiple clinical data sets." (PMID 25659579, 2015). "HACE1 plays a therapeutic role in degenerative diseases such as neurodegenerative diseases, cardiovascular diseases and cancer." (PMID 40948788, 2025). "Pharmacological and genetic modulation of HACE1 expression holds potential therapeutic value in age-related diseases such as neurodegenerative disorders, cardiovascular diseases, and cancer." (PMID 40948788, 2025). "This includes interaction with the potential tumor suppressor gene HACE1, indicating a complex interplay between viral and host genomic elements in cancer regulation." (PMID 40425856, 2025). "Of the other 16 genes, COL5A1, GABBR1, HACE1, EPHA7, and TRIP11 have well-documented associations with cancer." (PMID 30962767, 2019). "HACE1 E3 ligase was discovered to be down‐regulated in several cancers while its role in regulating tumors was merely understood." (PMID 29673126, 2018). "Our search of the Catalogue of Somatic Mutations in Cancer (COSMIC, version 64) database identified 13 missense mutations located in the ANK-MID region of HACE1 (amino-acids 1–545)." (PMID 28317937, 2017). "Consistently, stable co-knockdown of RAC1 in HACE1 deficient cells inhibits HIF1α accumulation in these cells, suggesting targeting of RAC1 is a potential mechanistic intervention point for targeted therapy in diverse cancer types." (PMID 33603169, 2021). "HACE1 is a tumour suppressor gene involved in different types of cancers." (PMID 30344923, 2018). "Moreover, HACE1 also controls cell growth, migration and invasion, which are key features of cancer progression." (PMID 29362425, 2018). "However, the implication of HACE1 in human disease is not limited to cancer." (PMID 35678127, 2022). "Thus, NKX6.3 inactivation in gastric mucosa may increase activity of NF-kB and DNMT1 and reduce Hace1 expression, subsequently progressing to atrophy, intestinal metaplasisa and cancer." (PMID 28584243, 2017).
cancer (continued). "To gain insight into the function of the non-catalytic ANK and MID domains of HACE1 and their role in cancer, we reasoned that missense mutations identified in cancer samples in these domains may reflect defects in their functions leading to impaired control of cell proliferation." (PMID 28317937, 2017). "In another study, the downregulation of HACE1 and OPTN proteins was observed in various cancers." (PMID 39859167, 2025).
neurodevelopmental disorder (8 papers, 2017 to 2025). A behavioral and cognitive disorder with onset during the developmental period that involves impaired or aberrant development of intellectual, motor, or social functions. "STRING analysis predicts the interaction of HACE1 with several proteins known to be implicated in human neurodevelopmental disorders." (PMID 38790209, 2024). "Nagy V. also proved that HACE1 is implicated in the formation of neurodevelopmental disorders by using HACE1 knock-out mice, which displayed many clinical features of SPPRS." (PMID 36553453, 2022). "Altogether, our results demonstrated that HACE1 mutations lead to a severe neurodevelopmental disorder by targeting key physiological processes such as autophagy, mitophagy and the ability to properly respond to oxidative damage." (PMID 32225089, 2020). "Here, we report 2 novel mutations in HACE1, p.Q209* and p.R332*, discovered in 3 patients from 2 unrelated consanguineous families with a complex neurodevelopmental disorder." (PMID 31321300, 2019). "An exome sequencing analysis identified aberrant functional mutations in HACE1, which leads to autosomal recessive neurodevelopmental disorders with ID, spasticity, and abnormal gait." (PMID 28579943, 2017). "Recessive HACE1 mutations are associated with a severe neurodevelopmental disorder (OMIM: 616756)." (PMID 32225089, 2020). "Consanguinity and possibly endogamy may be essential factors in the generational transmission of these harmful autosomal recessive mutations, as evidenced by the variety of loss-of-function mutations in the HACE1 gene linked to a familial neurodevelopmental disorder reported in independent reports." (PMID 38899231, 2024). "HACE1, along with UPS proteins, shows an anti-inflammatory effect by downregulating the IRF3 and NF-κB activation pathways, hence showing the involvement of UPS and HACE1 in immune-related pathogenesis and neurodevelopmental disorders." (PMID 38790209, 2024). "This case report is the third case in the Middle East and the second in Saudi Arabia to document the involvement of the HACE1 gene in a neurodevelopmental disorder." (PMID 38899231, 2024). "This is supported by the diverse functions of HACE1 in cellular processes such as tumorigenesis, oxidative stress response, and neurodevelopmental disorders." (PMID 32616021, 2020). "To date, the pathogenic HACE1 variants are limited to 14 LoF mutations, as reported in the HGMD Professional Database v.2022.1; no gross deletions have been described as the cause of this neurodevelopmental disorder." (PMID 36553453, 2022).
neurodegenerative disease (4 papers, 2017 to 2025). A disorder of the central nervous system characterized by gradual and progressive loss of neural tissue and neurologic function. "Recently, an increasing number of studies have indicated that HACE1 inactivation is strongly associated with poor prognosis in neurodegenerative diseases, cardiovascular diseases, and tumors." (PMID 40948788, 2025). "At the same time, growing evidence suggests that HACE1 also plays a crucial role in degenerative diseases." (PMID 40948788, 2025). "In recent years, researchers have increasingly discovered that HACE1 plays a vital role in the pathological process of many degenerative diseases." (PMID 40948788, 2025). "These cumulative results suggest that HACE1 can serve as an early stage neurodegenerative disease target." (PMID 33435370, 2021). "Another E3 ubiquitin ligase HACE1, which has an essential implication in NDDs and neurodegenerative diseases, also demonstrates an insight into the relationship between QC mechanism and neurobiological functions." (PMID 28579943, 2017). "Therefore, targeting HACE1 to inhibit the Rac1 signaling pathway to alleviate cellular oxidative stress would be an effective therapeutic strategy in degenerative diseases." (PMID 40948788, 2025). "Further evaluation into this prominent domain within HACE1 can also potentially identify abnormalities in substrate recognition and binding the AR domain typically takes on, which can lead towards the development of neurodegenerative disease treatment." (PMID 33435370, 2021). "Recent research has found that HACE1 (HECT domain and ankyrin repeat-containing E3 ubiquitin-protein ligase 1) serves as a stress-protective gene that plays a crucial role in heart diseases, neurodegenerative diseases, and tumors." (PMID 40948788, 2025).
neurological disorders (3 papers, 2022 to 2024). "To date, ten protein truncating, one in-frame deletion, and one missense variants in HACE1 have been reported in subjects with neurological disorders, and our study represents the second known case of HACE1 disorder associated with a novel missense allele." (PMID 38790209, 2024). "Specifically assessing the HECW2 (R1330W) and HACE1 (R585W) mutants, this arginine residue is relatively conserved in the N-lobe and linked to the onset of neurological disorders." (PMID 36111624, 2022).
heart diseases (1 paper, 2025). "In addition to inhibiting neurodegeneration, HACE1 has been reported to activate the Nrf2/ARE signaling pathway, upregulate HO-1 and NQO1 antioxidant genes, and attenuate H/R-induced oxidative stress and inflammation, making it a promising therapeutic target and predictor of cardiac disease." (PMID 40948788, 2025).
mitochondrial disease (1 paper, 2020). "As the patient phenotype was compatible with a mitochondrial disease, we performed a fractionation analysis to determine the subcellular localization of HACE1 in control fibroblasts and evaluate whether HACE1 could be associated to mitochondria." (PMID 32225089, 2020).
HACE1 also shares sentences with these, for which no sentence is quoted: leukemia (3 papers); cerebellar ataxia (2); alveolar rhabdomyosarcoma (1); Anxiety (1); Atrophy (1); Autosomal Recessive Spastic Paraplegia (1); cardiovascular diseases (1); embryonal rhabdomyosarcoma (1); epilepsy (1); genetic disease (1); glioblastoma (1); hepatocellular carcinoma (1); infection (1); invasive breast carcinoma (1); lymphoma (1); mammary adenocarcinoma (1); ovarian tumours (1); pancreatic cancers (1); Parkinson disease (1); prostate carcinoma (1); synovial sarcoma (1); virus infection (1).